SNORD36 (Small nucleolar RNA SNORD36 )
Synonyms: LOC124903254
Gene: Small nucleolar RNA gene on chromosome 13 (22,803,145 to 22,803,224, forward strand). Ensembl gene ENSG00000253094.
Gene Ontology:
Biological process: RNA processing
Cellular component: nucleolus
Homologues: Orthologues: chimpanzee SNORD36 (95% identical), macaque SNORD36 (65% identical), rat LOC120101982 (62% identical), mouse Gm24134 (61% identical), pig SNORD36 (61% identical), guinea pig SNORD36 (59% identical), dog SNORD36 (56% identical). Paralogues in human: SNORD36A (65% identical), SNORD36B (51% identical), SNORD36C (40% identical).